INS (insulin)
Diseases named in the same sentence as INS in open-access papers (continued):
Sharing a sentence is not in itself a finding about the gene and the disease.
Obesity (continued). "Over the course of obesity, ectopic fat deposition (known as visceral adiposity) leads to a low grade of chronic inflammation, insulin resistance, and an altered adipokine profile, which can shape a pro-tumoral microenvironment supporting malignant transformation and progression." (PMID 33333960, 2020). "Studies have documented an inverse correlation between cellular miRNA-187 levelss and glucose-stimulated insulin secretion and that miRNA-378a may play a role in insulin resistant and the consequent of obesity." (PMID 32168775, 2020). "High-fat diet and obesity induce ER stress in muscles and subsequently suppress insulin signaling." (PMID 32831068, 2020). "Obesity is associated with metabolic endotoxemia, and lipopolysaccharides (LPS) derived from the cell wall of Gram-negative bacteria can impair insulin clearance." (PMID 32860984, 2020). "Under conditions of obesity, peripheral tissues experience a decrease in sensitivity to insulin." (PMID 31941045, 2020). "Our results suggested that obesity may partially affect the pathologic development of TC through its influence on the INS levels." (PMID 33240576, 2020). "Thus, in the context of obesity, the convergence of chronic inflammation, insulin signaling dysregulation, altered availability of lipids and other macromolecules as well as changes in adipokine signaling appear to be involved in the pathogenesis of cancer." (PMID 32824322, 2020). "The interaction of HGI and obesity may increase the occurrence of hypertension through co-owned mechanisms, such as inflammatory responses and insulin resistance." (PMID 33148181, 2020). "This movement of chromium may have enhanced insulin signaling and reduced obesity-induced hyperglycemia levels." (PMID 32260278, 2020). "However, currently there is insufficient research on the ground of CBDV's effects on obesity, insulin resistance and other metabolic disturbances." (PMID 32194509, 2020). "Xbp1+/− mice exhibit increased ER stress coupled with impaired glucose and insulin tolerance in the high fat diet (HFD)-induced obesity, but in pathological manifestations, activated IRE1α modulates many downstream molecules which consequently result in disease progression." (PMID 32397116, 2020). "The miR-103 expression could be related to impaired insulin sensitivity and glucose uptake, possibly an attractive pharmacological target in obesity and diabetes, promoting cell adipogenesis by targeting MEF2D and activating AKT/mTOR signaling pathway." (PMID 33123088, 2020). "How does obesity amplify the actions of insulin (and leptin) on POMC neurons in males?" (PMID 32160920, 2020). "Moreover, it has been observed that the dysfunction of adipose is connected with changes in brain metabolism, brain atrophy, cognitive decline, impaired mood, neuroinflammation, impaired insulin signaling, and neuronal dysfunction in people with obesity." (PMID 33584324, 2020). "A report from the International Agency for Research on Cancer concluded that there was strong evidence for chronic inflammation and sex hormone metabolism mediating the relationship between obesity and cancer, whilst evidence for insulin and IGF signalling was moderate." (PMID 32069845, 2020). "Asinine metabolic syndrome (AMS) comprises obesity, insulin dysregulation, and laminitis." (PMID 33302557, 2020). "Several factors such as obesity, recurrent GDM, higher glucose levels during pregnancy, and an insulin requirement during pregnancy may influence the risk of persistent postpartum glucose intolerance." (PMID 32500037, 2020). "Our data demonstrate that a high‐fat diet stimulates the expected hallmark obesity and an insulin‐resistant state but SA treatment had no clear positive effect." (PMID 33185326, 2020).
Obesity (continued). "Elevated cysteine was suggested to be a cause rather than a consequence of obesity, by promoting lipogenesis, inhibiting lipolysis, decreasing energy expenditure and decreasing insulin sensitivity, thus favoring lipid storage via unspecified pathways." (PMID 32957568, 2020). "This suggests that in addition to exercise, calorie restriction may protect the liver from obesity-driven insulin resistance more so than training alone, despite comparable peripheral insulin sensitivity." (PMID 32849302, 2020). "Obesity also affects skeletal muscle, increasing LD and producing insulin signaling impairment." (PMID 32151028, 2020). "Partly, these results may be attributed to the increased production of estrogen secondary to the aromatase activity in breast adipose tissue; additionally, obesity increases inflammatory cytokines, circulating insulin, and IGF-1 levels." (PMID 33180852, 2020). "We conclude that gut microbes regulate insulin clearance during diet-induced obesity." (PMID 32860984, 2020). "Furthermore, knockout of KLK7 in adipose tissue preserved insulin sensitivity in obesity by counteracting adipose tissue inflammation under high-fat diet in vivo." (PMID 32344508, 2020). "Regarding the relationship between sarcopenia and obesity, elevated insulin resistance—which results in obesity and metabolic syndrome—was found in patients with sarcopenia, probably because of their reduced available insulin-response muscle." (PMID 32344580, 2020). "Moreover, SCFA administration in animal models of obesity decreases the accumulation of fat in the liver and improves insulin resistance through mechanisms involving liver glycogenesis and lipogenesis." (PMID 32487227, 2020). "Subjects with low GIP, despite obesity, seemed to be insulin sensitive and normolipemic." (PMID 32069846, 2020). "Moreover, obesity and chronically high levels of insulin disrupt the metabolic sensing of the OBs in mice." (PMID 33328935, 2020). "The re-emergence of the concept that pancreatic beta-cells’ insulin hyper-responsiveness to nutrient-stimulus might be the factor triggering obesity, warrants further investigation." (PMID 32630256, 2020). "It seems to improve insulin sensitivity, but also promotes obesity." (PMID 33178196, 2020). "Biologically, arguments explaining why activity intensity may be relevant to obesity are speculative, including appetite regulation and insulin sensitivity improvement." (PMID 32784949, 2020). "For instance, obesity is associated with a low-grade chronic inflammatory state, characterized by increased production of inflammatory mediators, together with enhanced IGF-1 and insulin signaling." (PMID 33364239, 2020). "Higher basal GU in obesity could be partially explained by marginally higher insulin concentrations in the obese subjects with T2DM (mean 20.6 mU/L) or without T2DM (15.7 mU/L) when compared to the controls (7.1 mU/L, P = 0.06)." (PMID 32311037, 2020). "In addition, animal models have demonstrated that sex and sex hormones influence adipose tissue, gene expression profiles, regulating insulin resistance and lipolysis, as well as inflammatory tone and obesity." (PMID 32987732, 2020). "We hypothesized that gut microbes also regulate insulin clearance, which could contribute to post-prandial hyperinsulinemia during diet-induced obesity." (PMID 32860984, 2020). "Insulin secretion is tightly controlled by feedback from the beta cells, plasma glucose, incretin hormones, insulin sensitivity, and neuronal controls like hyperglycemia, obesity, hyperlipidemia, oxidative stress, inflammation, and amyloid deposition, which can accelerate the beta-cell loss." (PMID 32399348, 2020). "Furthermore, induction of SCD1 and production of palmitoleate can rescue insulin sensitivity in murine models of obesity and insulin resistance." (PMID 32198362, 2020). "In conclusion, we found that RYGB upregulates genes involved in obesity and insulin pathways." (PMID 32599690, 2020).
Obesity (continued). "In obesity, excess circulating fatty acids in plasma may accumulate ectopically in insulin-sensitive tissues and impair insulin action." (PMID 33841133, 2020). "Finally, we examined body composition and metabolic derangements including inflammatory processes, insulin resistance, and adipokines as potential contributing factors to obesity-enhanced CRC." (PMID 33346251, 2020). "Notably, the OBs have a high density of insulin and leptin receptors, hormones that are elevated in obesity and involved in homeostatic signaling as well as in modulating odor sensitivity." (PMID 33328935, 2020). "Thus, the preventive effect of kaempferol on obesity-related complications is possibly attributable to the weakened pathological processes of insulin resistance and inflammation." (PMID 32337249, 2020). "In a small pilot trial, conducted in the Netherlands, 9 men with obesity who received endoscopically delivered FMT infusions from lean donors had significantly improved peripheral insulin sensitivity over 6 weeks as assessed by hyperinsulinemic euglycemic clamp." (PMID 32150549, 2020). "Also fibroblast growth factor 21 (FGF21) has anti-inflammatory properties in obesity related inflammation and is observed to increase sensitivity to insulin." (PMID 32471255, 2020). "Likewise, upregulation of BRD7 improves insulin signaling in obesity, but inhibits PI3K activity in a cancerous state." (PMID 32992509, 2020). "Moreover, in mice, treatment with butyrate improves insulin sensitivity and increases energy expenditure, leading to reduced obesity." (PMID 32487227, 2020). "Moreover, the potential of asiatic acid as an anti-obesity agent can be proved from the facts that it suppresses weight gain, and enhance the sensitivity of leptin and insulin." (PMID 33013406, 2020). "Murine and in vitro studies show that increased signaling through GPCRs, mediated by acetate, propionate, and butyrate, increases satiety and insulin sensitivity, while decreasing adipogenesis; yet, we did not observe associations between fecal SCFA levels and metrics of obesity." (PMID 32788375, 2020). "RT-PCR performed in our laboratory indicated that P2Y2 receptor is expressed in organs or tissues involved in the development of obesity and insulin resistance, such as skeletal muscle, intestines, liver, pancreas, and white and brown adipose tissues (data not shown)." (PMID 32582029, 2020). "It has been increasingly recognized that parasite derived excretory-secretory products (ESPs), the key substances employed by helminths to downregulate the host’s anti-infection immunity, are able to regulate adipogenesis and improve insulin sensitivity in a high fat diet-induced obesity model." (PMID 32973568, 2020). "Similarly, adipose tissue expression of Tnfα is elevated in obesity (Hotamisligil, Shargill, & Spiegelman, 1993) and aging, and inhibition of Tnfα improves insulin sensitivity." (PMID 32512652, 2020). "But, to date, the association between the intestinal insulin signalling pathways and the remission of obesity and T2DM after bariatric surgery has not been explored." (PMID 31936857, 2020). "Since insulin is an important mediator of obesity-related pathologies, we will focus in the next section on brain insulin and how elevated insulin levels may relate to neurodegenerative disorders." (PMID 33384592, 2020). "Over the years, several lines of evidence have outlined a critical role of the adenosine system in glucose homeostasis, inflammation, adipogenesis, insulin resistance and thermogenesis, thus suggesting an involvement of adenosine in the onset and progression of obesity." (PMID 33536924, 2020). "Indeed, co-administration of Fat1562 with anti-TNFα led to a striking increase of VAT-Treg cells and a significant improvement in insulin sensitivity in mice with severe obesity." (PMID 32773038, 2020). "•Obesity impairs insulin clearance in mice, which is mitigated by antibiotics." (PMID 32860984, 2020).
Obesity (continued). "Free fatty acids (FFA) in plasma may be intermediaries in impaired insulin sensitivity and glucose tolerance related to obesity and T2DM." (PMID 32796637, 2020). "It is considered a drug that is beneficial for some pathologies, such as obesity, since it reduces intake of food and weight gain, prevents hyperinsulinemia, improves insulin sensitivity, and improves blood glucose and lipid profile, which together counteracts mitochondrial dysfunction." (PMID 33291828, 2020). "Our data add microbe-specific regulation of insulin clearance to the growing body of evidence that specific microbes influence dynamic insulin and glucose responses and these endocrine and metabolic responses are altered by changes in the host–microbe relationship during obesity." (PMID 32860984, 2020). "These medications could even counter some GC side effects by enhancing insulin sensitivity, preventing obesity, hypertension and mood disturbances." (PMID 32283840, 2020). "In this context, current evidence suggests that SST and its analogues, through binding to different SSTR subtypes on the pancreatic β-cells, decrease the release of insulin, which may be beneficial in the treatment of obesity." (PMID 32272767, 2020). "Among the benefits are the improvement of glucose-stimulated insulin secretion, the decrease in IR, fasting glucose levels and body fat, and the increase in fat-free mass, which may consequently help reduce obesity, T2D, and IR32." (PMID 33037261, 2020). "In contrast, administration of human insulin worsened both obesity and steatosis." (PMID 33679386, 2020). "Moreover, in obesity, adipose tissue develops resistance to insulin-mediated suppression of lipolysis which enhances the release of small EVs enriched in adipose fatty acid binding protein (aP2), leading to amplified liver glucose output and diabetes." (PMID 33339409, 2020). "Thus, insulin also contributes to obesity-induced activation of central sympathoexcitatory pathways in males." (PMID 32160920, 2020). "We therefore hypothesized that the elevation in methylated INS and CHTOP-817 in our populations might reflect concurrent systemic inflammation related to the underlying T1D or overweight/obesity." (PMID 32736653, 2020). "Interestingly, we found that, despite obesity, mice with reduced neuronal LPL showed improved glucose tolerance with aging, a phenotype that involves reduced hepatic EGP and preserved hepatic insulin sensitivity despite aging and obesity." (PMID 32998280, 2020). "Additionally, on diet induced obesity CerS5 knockout animals displayed improved glucose tolerance, insulin sensitivity, and reduced white adipose inflammation compared to wild type animals." (PMID 32849276, 2020). "Previous studies have shown that circulating pipecolate levels were strongly associated with obesity and metabolic syndrome and had the ability to predict the risk of future T2DM, HG, increasing insulin secretion in early IR, and had a lesser role in the setting of advanced IR or T2DM." (PMID 33381523, 2020). "Under normal physiological conditions, skeletal muscle is responsible for most insulin‐stimulated glucose disposal in the body; therefore, skeletal muscle dysfunction due to obesity can robustly impact glucose homeostasis and insulin sensitivity; thus, possibly leading to a diabetic state." (PMID 33185326, 2020). "Interestingly, the reductions of PLIN1 and FASN expression are individually reported as improving resistance to HG-induced obesity and insulin sensitivity and reducing adipose tissue inflammation." (PMID 33003504, 2020). "Notably, IRF5 has been implicated with macrophage polarization toward an inflammatory M1 phenotype as well as adipose deposition and insulin sensitivity in obesity." (PMID 31718015, 2019). "In addition, Gogas and colleagues suggest a possible role in melanoma development of high circulating levels of leptin, a factor involved in glucose metabolism and directly related with obesity, insulin levels and female sex." (PMID 31547443, 2019).
Obesity (continued). "The coexistence of deregulated insulin signaling in obesity has been well-known for decades." (PMID 31380268, 2019). "Postprandial glucose and insulin were greater following the carbohydrate compared with the high-protein meal, and this was more marked in adolescents with obesity compared with those of healthy weight (time × weight × meal interaction, p = 0.003 and p = 0.018, respectively)." (PMID 30764560, 2019). "However, patients with T2DM and/or obesity showed decreased insulin levels in the cerebrospinal fluid despite higher levels of this hormone in their plasma." (PMID 31417349, 2019). "Severe obesity (body mass index ≥35 or ≥40 after January 1, 2017, as indicated with a procedure-fee modifier), chronic inflammation (all measures of C-reactive protein >10 mg/L), and a surrogate measure of insulin resistance." (PMID 31469399, 2019). "If BCAAs elevation is rather the consequence of a disturbed metabolism, it has been proposed that high fat diets, obesity, IR or insulin levels could lead to a defect in BCKD activity and expression in the liver." (PMID 30650556, 2019). "Furthermore, troxerutin can prevent obesity by improving the insulin signaling pathway and returns blood glucose, fatty acids, and cholesterol levels to normal levels." (PMID 31231491, 2019). "Adverse health consequences of obesity are observed in many western populations and include higher blood pressure, obesity, glucose intolerance, dyslipidemia, decreased insulin sensitivity, and type 2 diabetes, which are components of metabolic syndrome (MetS)." (PMID 31744052, 2019). "Recently, in a diet-induced obesity mouse model it was shown that acute administration of apelin-13 and analogues with enhanced in vitro plasma stability resulted in improved glucose homeostasis and insulin secretion." (PMID 31472173, 2019). "Moreover, ezetimibe improves not only lipid profiles, but also atherogenic factors and biomarkers, such as hepatocyte growth factor and insulin resistance, in patients with obesity and hypercholesterolemia." (PMID 30519809, 2019). "However, there is controversy about the impact of liposuction on obesity endpoints like insulin sensitivity." (PMID 31178685, 2019). "Obesity in childhood is the main determinant of whole body reduced insulin sensitivity." (PMID 31474943, 2019). "Indeed, SAT expansion is protective in obesity while VAT expansion promotes the metabolic complications of obesity such as resistance to insulin and type 2 diabetes." (PMID 31223312, 2019). "The aim of this study was to evaluate if EAE and two compounds identified in EAE (MA and myricetin [MYR]) could have a beneficial effect on systemic and vascular insulin sensitivity and endothelial function in a model of diet-induced obesity." (PMID 30679477, 2019). "Taken together, these data demonstrate that PDH-mediated glucose oxidation, which increases in response to insulin in obesity-associated but not obesity-independent tumor cell lines, drives cell division in these six tumor models, at least in in vitro culture." (PMID 31188872, 2019). "Through this test, we could first observe that obesity alone was able to decrease insulin sensitivity when comparing the CG to the OG (p < 0.05)." (PMID 31827186, 2019). "Additionally, TUDCA was demonstrated to be a major helper in counteracting obesity-induced hyperinsulinemia in the liver of high-fat-diet-fed C57Bl/6 mice due to improved insulin clearance." (PMID 31757001, 2019). "However, only male PHB-Tg mice displayed obesity-related metabolic dysregulation, such as impaired glucose homeostasis, insulin sensitivity, and hyperinsulinemia." (PMID 31118075, 2019). "Indeed, a prediction of this model is that induction of SWELL1 protein expression, SWELL1-LRRC8 activity and VRAC current is a feature of early, normoglycemic obesity that supports healthy adipocyte expansion and maintains insulin-sensitivity." (PMID 31112068, 2019).